C1QTNF4 (C1q and TNF related 4)
Description:
May be involved in the regulation of the inflammatory network. Its role as pro- or anti-inflammatory seems to be context dependent. Seems to have some role in regulating food intake and energy balance when administered in the brain. This effect is sustained over a two-day period, and it is accompanied by decreased expression of orexigenic neuropeptides in the hypothalamus 3 hours post-injection (By similarity).
Synonyms: CTRP4; ZACRP4
Tractability: Antibody: UniProt places it where antibodies can reach, with high confidence; UniProt predicts a signal peptide or a membrane-spanning region; its Gene Ontology location is reachable by antibodies, with medium confidence. PROTAC: its protein half-life has been measured.
Gene: Protein-coding gene on chromosome 11 (47,589,666 to 47,595,642, reverse strand). Ensembl gene ENSG00000172247.
Subcellular location: Secreted
Subcellular location (Human Protein Atlas): Golgi apparatus; Vesicles; Predicted to be secreted
Gene Ontology:
Molecular function: protein binding
Biological process: positive regulation of interleukin-6 production; positive regulation of interleukin-6-mediated signaling pathway; positive regulation of non-canonical NF-kappaB signal transduction; positive regulation of tumor necrosis factor production
Cellular component: extracellular region
Genetic constraint (gnomAD): Loss-of-function variants: 14 observed, 11.72 expected, observed/expected ratio (o/e) 1.2, 90% interval 0.79 to 1.78. The synonymous counts are far from expectation, so gnomAD's model fits this gene poorly and the ratio says little. Missense variants: 558 observed, 441.25 expected, observed/expected ratio (o/e) 1.26, 90% interval 1.18 to 1.36. Synonymous variants: 278 observed, 214.97 expected, observed/expected ratio (o/e) 1.29, 90% interval 1.17 to 1.43.
Homologues: Orthologues: macaque C1QTNF4 (96% identical), mouse C1qtnf4 (94% identical), rat C1qtnf4 (93% identical), pig C1QTNF4 (93% identical), guinea pig C1QTNF4 (89% identical), tropical clawed frog c1qtnf4 (58% identical), zebrafish c1qtnf4 (56% identical), dog C1QTNF4 (29% identical). Paralogues in human: C1QTNF5 (21% identical), C1QL4 (20% identical), C1QTNF2 (20% identical), COL10A1 (20% identical), COL8A2 (20% identical), ADIPOQ (19% identical), C1QTNF8 (19% identical), C1QL2 (19% identical), C1QL3 (19% identical), C1QTNF7 (19% identical), C1QL1 (19% identical), COL8A1 (18% identical), and 11 more.
Diseases named in the same sentence as C1QTNF4 in open-access papers:
C1QTNF4 is named in the same sentence as 33 diseases in open-access papers, as found by Europe PMC text mining. Sharing a sentence is not in itself a finding about the gene and the disease. The quoted sentences say what the papers report.
Obesity (3 papers, 2021 to 2026). Accumulation of substantial excess body fat. "This study suggests that C1QTNF4 represents a potential drug target for treating obesity, IR, and inflammation." (PMID 42106023, 2026).
Arterial stenosis (1 paper, 2023). Narrowing or constriction of the inner surface (lumen) of an artery. "Serum C1QTNF4 levels were decreased in patients with arterial stenosis." (PMID 37221646, 2023).
autoimmune disease (1 paper, 2023). A disorder resulting from loss of function or tissue destruction of an organ or multiple organs, arising from humoral or cellular immune responses of the individual to their own tissue constituents. "In addition, exome sequencing of systemic lupus erythematosus patients identified a rare mutation of CTRP4/C1QTNF4 (H198Q) that inhibited TNF-mediated NF-κB activation and cell death, suggesting potential role of CTRP4 in autoimmune diseases." (PMID 38015631, 2023).
cancer (4 papers, 2014 to 2024). A tumor composed of atypical neoplastic, often pleomorphic cells that invade other tissues. "The implication of the inflammatory pathway in AD pathogenesis and the inverse association between AD and cancer may explain in part the observed relationship between these SNPs and their effect on C1QTNF4 expression." (PMID 24743338, 2014). "C1QTNF4 is an inflammatory cytokine capable of activating both Stat3/IL6 and NF-κB pathways, as shown in cancer cells." (PMID 24743338, 2014).
tumour (3 papers, 2018 to 2023). "We first identified C1QTNF4 in 2011 and it has shown the ability to potentiate tumour cell survival and resistance against apoptosis by activating both the NF‐κB and IL6/STAT3 pathways." (PMID 37221646, 2023). "Among the C1QTNFs, C1QTNF4 is the only member with two C1q globular domains and has previously been reported to function in the hypothalamus and in tumour cell survival." (PMID 37221646, 2023). "Gene c1qtnf4 can promote tumour cell survival and tumour resistance against apoptosis induced by chemotherapeutics." (PMID 33987975, 2021).
cardiovascular disease (1 paper, 2023). "Considering the unique structure of C1QTNF4 and the relationship between cardiovascular disease and some of the C1QTNF family members, we investigated the role of C1QTNF4 in blood vessels." (PMID 37221646, 2023). "To date, there is very little published literature on C1QTNF4 in cardiovascular disease." (PMID 37221646, 2023).
infection (1 paper, 2023). The state of being infected such as from the introduction of a foreign agent such as serum, vaccine, antigenic substance or organism. "Recently, a c1qtnf4 gene was upregulated 3 days post-infection in a clonal line of rainbow trout exhibiting high susceptibility to BCWD but was not regulated in two other lines with either intermediate or higher relative resistance." (PMID 37928534, 2023).
infectious disease (1 paper, 2021). A disorder directly resulting from the presence and activity of a microbial, viral, or parasitic agent in humans. "Another species, C. burnetii, was mainly positively correlated with infectious disease-related genes like RAB2B, MICA, C1QTNF4, and YF6." (PMID 35250914, 2021).
C1QTNF4 also shares sentences with these, for which no sentence is quoted: acute coronary syndrome (2 papers); diabetes mellitus (2); herpes simplex encephalitis (2); lung carcinoma (2); atherosclerosis (1); breast carcinoma (1); carotid atherosclerosis (1); colitis (1); colon cancer (1); colorectal cancer (1); endothelial dysfunction (1); experimental autoimmune encephalomyelitis (1); Hashimoto thyroiditis (1); Hyperglycemia (1); Hypertension (1); Insulin resistance (1); liver cancer (1); osteosarcoma (1); ovarian carcinoma (1); prostate carcinoma (1); renal cell cancer (1); Sepsis (1); systemic lupus erythematosus (1); type 2 diabetes mellitus (1); ulcerative colitis (1).